GLP1R (glucagon like peptide 1 receptor)
Diseases named in the same sentence as GLP1R in open-access papers (continued):
Sharing a sentence is not in itself a finding about the gene and the disease.
Obesity (continued). "Over the past few years, glucagon-like peptide-1 receptor agonists (GLP-1 RAs) have revolutionized the management of type 2 diabetes and recently have emerged as a promising therapeutic option for obesity." (PMID 41230299, 2025). "Such agents are now well-established for treating obesity and T2D in humans, and therapies combining GIPR antagonism with GLP-1R agonism have also shown promising results in clinical studies." (PMID 40024571, 2025). "Glucagon-like peptide-1 receptor agonists (GLP-1 RAs), initially developed for type 2 diabetes and obesity, have emerged as promising candidates to address this metabolic–psychiatric interface." (PMID 41010364, 2025). "There was an upsurge of GIP focused research since the extended-release GLP-1R and GIPR co-agonist tirzepatide became available for T2D and obesity treatment." (PMID 40687579, 2025). "Pharmacologic therapies, particularly glucagon-like peptide-1 receptor agonists and newer dual agonists (GLP-1s), have emerged as promising treatments for obesity." (PMID 41209422, 2025). "Semaglutide, a glucagon-like peptide-1 receptor agonist (GLP-1RA), is the first of these new agents to obtain regulatory approval for the treatment of obesity, with tirzepatide and other drugs showing even stronger potential." (PMID 38459258, 2025). "In prior phase II trials, survodutide (BI 456906), a once-weekly dual GLP-1R/GCGR agonist, has shown significant efficacy in reducing body weight and hyperglycemia in individuals with obesity and/or T2DM." (PMID 40004572, 2025). "And yet, undeterred, dual agonism of GLP-1R and GIPR has also progressed and, in fact, achieved regulatory approval first for both T2D and obesity indications in the form of unimolecular co-agonist tirzepatide." (PMID 40507574, 2025). "In this context, glucagon-like peptide-1 receptor agonists (GLP-1 RAs), a novel class of antidiabetic and anti-obesity agents, have gained widespread recognition for their safety, efficacy, and metabolic benefits in managing T2DM and obesity." (PMID 40697657, 2025). "For example, genetic variants in GLP-1R (glucagon-like peptide-1 receptor) and GIPR (glucose-dependent insulinotropic polypeptide receptor) may modulate the effectiveness of incretin-based therapies, while PRS for satiation can help match individuals to the most appropriate anti-obesity medications." (PMID 41009961, 2025). "In this review, we focus on four key metabolic GPCRs—GPR40, GPR120, GLP-1R, and β-adrenergic receptors (ADRB1, ADRB2, and ADRB3)—with respect to their roles in metabolic physiology and significance in obesity and related metabolic diseases." (PMID 40001594, 2025). "Glucagon-like peptide-1 receptor agonists (GLP-1 RAs) are established treatments for type 2 diabetes mellitus and obesity." (PMID 40943907, 2025). "This study assesses the efficacy and safety of the novel oral small molecule glucagon-like peptide-1 receptor agonists (GLP-1 RAs) danuglipron and orforglipron in the treatment of type 2 diabetes (T2DM) and obesity through systematic review and meta-analysis." (PMID 41450584, 2025). "For example, basal hypothalamic IL-6 level and microglia function maintain hypothalamus homeostasis, which is critical to GLP-1/GLP-1R-mediated food intake control, and its disturbance may impact systemic infections, such as bacterial sepsis and other inflammatory conditions as seen in obesity." (PMID 40592472, 2025). "Among these, glucagon-like peptide-1 receptor agonists (GLP-1RA), such as liraglutide, exenatide, and semaglutide, have emerged as effective treatments for obesity and its related metabolic decrease." (PMID 40427764, 2025). "In recent years, glucagon-like peptide-1 receptor agonists (GLP-1 RAs), originally developed for the treatment of type 2 diabetes and obesity, have drawn increasing attention in the context of chronic inflammatory diseases." (PMID 40917833, 2025).
Obesity (continued). "Recent pharmaceutical interventions, specifically glucagon-like peptide-1 receptor agonist drugs (GLP-1RA), have advanced medical treatment for obesity and glycemic control." (PMID 40352260, 2025). "Incretin‐based therapies using single agonists towards GLP‐1 receptor (GLP‐1R) or GIP receptor (GIPR) and dual agonists towards GLP‐1R/GIPR have proven to be effective therapeutic options in type 2 diabetes (T2D), obesity, and related CVDs." (PMID 40838278, 2025). "Twenty-four patients with obesity and T2DM undergoing insulin therapy were randomly assigned to receive either exenatide (a glucagon-like peptide-1 receptor agonist) or a placebo twice daily for 12 weeks." (PMID 41109135, 2025). "Thus, while GLP-1R agonist treatment suppresses tumors in these models, the triple agonist (retatrutide) may have a more prominent, and potentially durable, antitumor effect in the context of obesity." (PMID 41178720, 2025). "The drug Tirzepatide is a dual glucose-dependent insulinotropic polypeptide (GIP) and glucagon-like peptide-1 receptor (GLP1-R) agonist used for the treatment of T2DM and obesity." (PMID 41155431, 2025). "Glucagon-like peptide-1 receptor agonists (GLP-1 RAs), such as liraglutide and semaglutide, are effective obesity treatments." (PMID 40507203, 2025). "The receptors of the moment, however, and of broadest societal relevance, are the incretin hormone receptors, GLP1R and GIPR—both key targets for anti-obesity therapy development." (PMID 39910307, 2025). "GLP-1R agonists reportedly reduce macrophage infiltration and inflammation at WAT in experimental models of obesity." (PMID 40892365, 2025). "Glucagon-like peptide-1 receptor agonists (GLP-1RAs), including liraglutide, have revolutionized obesity management through their therapeutic efficacy, achieving an average of 8.0% weight loss in phase III clinical trials." (PMID 40475994, 2025). "Glucagon-like peptide 1 receptor agonists (GLP-1 agonists) are broadly used for the management of diabetes and obesity." (PMID 40822483, 2025). "Among the GLP1-R agonists, one of the most prescribed is liraglutide (LIG), which is used for treating type 2 diabetes and obesity." (PMID 40141063, 2025). "Tirzepatide is the first FDA-approved GLP-1R/GIPR agonist for treating T2D and more recently approved for the treatment of overweight or obesity." (PMID 38477666, 2024). "DNA methylation is closely related to the development of obesity by affecting gene expression, then disrupting the regulatory balance between obesity-promoting genes (such as FTO and PPARγ) and anti-obesity genes (such as LEP, GLP-1R, and POMC)." (PMID 39200098, 2024). "This meta-analysis aimed to compare the effectiveness of bariatric metabolic surgery (BMS) and glucagon-like peptide-1 receptor agonists (GLP-1RAs) on cardiovascular outcomes and mortality in patients with obesity." (PMID 39552962, 2024). "The resounding therapeutic success of the GIPR/GLP-1R co-agonist, tirzepatide, has seen a resurgence of interest in GIPR modulation for the management of T2DM and obesity (Nauck & Müller 2023)." (PMID 38861364, 2024). "Recently, several trials have included multi-targeting agonists of GLP-1R, GIPR, or glucagon receptor (GCGR) for the treatment of both T2D and obesity." (PMID 38850440, 2024). "Glucagon-like peptide-1 receptor agonists (GLP-1 RAs) are utilized in the treatment of T2DM and obesity, with agents such as semaglutide, albiglutide, dulaglutide, exenatide, liraglutide, and lixisenatide currently in use." (PMID 39337658, 2024). "The glucagon-like peptide-1 (GLP-1)/GLP-1 receptor (GLP-1R) system has emerged in recent years as the main anti-diabetic and anti-obesity drug target." (PMID 38909126, 2024). "Tirzepatide is the first unimolecular dual GIPR/GLP1R agonist for the treatment of T2DM and overweight/obesity." (PMID 39834741, 2024).
Obesity (continued). "The apparent synergy between GLP-1R mimetics and GIPR antagonists has been exploited elsewhere in the pursuit of GIP MABs for obesity management." (PMID 38861364, 2024). "Glucagon-like peptide-1 receptor agonists (GLP1-RA) are primarily used for type-2 diabetes [T2DM] and obesity therapy." (PMID 39457081, 2024). "Over the past decade, glucagon-like peptide-1 receptor agonists (GLP-1 RAs) have emerged as highly effective glucose and body-weight-lowering agents for individuals with type 2 diabetes (T2DM), obesity, or both." (PMID 39335625, 2024). "The findings suggest that a reduction of GLP-1R in PVN amplifies food consumption, leading to obesity." (PMID 38765635, 2024). "New generation anti-obesity medications (AOMs), particularly nutrient-stimulated hormone (NuSH)-based therapies such as glucagon-like peptide-1 receptor agonists (GLP-1 RAs), show promise in addressing the obesity pandemic." (PMID 39624804, 2024). "In this review we discuss the evolving role of semaglutide, which is a glucagon-like peptide-1 receptor agonist (GLP-1 RA) that has been already approved for the treatment of type II diabetes mellitus (T2DM) and obesity." (PMID 38464718, 2024). "Another promising therapeutic approach involves the use of glucagon-like peptide-1 receptor (GLP-1R) agonists, initially approved as anti-diabetic and anti-obesity drugs, have been studied for their potential benefits in obesity-related asthma." (PMID 39554494, 2024). "Glucagon-like peptide-1 receptor agonists (GLP-1RAs) are a class of medications commonly used in the treatment of type II diabetes mellitus and, more recently, obesity." (PMID 38421490, 2024). "Tirzepatide, the first dual agonist for the treatment of T2DM and obesity targeting GIPR and GLP-1R, was approved by the U.S. FDA in 2022." (PMID 36677809, 2023). "Glucagon-like peptide-1 receptor analogs (GLP-1 RAs) have been an innovative and instrumental drug class in the management of both type 2 diabetes and obesity." (PMID 37526853, 2023). "At present, more compounds of receptors with dual agonists are being tested, for example, GLP-1R/GR (glucagon receptor), GLP-1R/AR (amylin receptor) and GLP-1R/NPYR (peptide YY binds to neuropeptide Y receptors), and might achieve further advances in T2DM, obesity and associated conditions therapy." (PMID 37904255, 2023). "Based on these findings, development of unimolecular dual GLP-1R/GCGR agonists has been carried out to obtain new and improved anti-obesity drugs." (PMID 37378828, 2023). "Compared with HRQOL reported in clinical trials of the glucagon-like peptide 1 receptor agonist semaglutide in patients with general obesity, patients with BBS reported comparable or worse baseline HRQOL than those with general obesity." (PMID 36647077, 2023). "Recently, several multi-targeting agonists of GIPR, GLP-1R, or GCGR for treating T2DM and obesity have been in clinical trials." (PMID 36843578, 2023). "Although numerous GLP-1R agonists are available clinically, semaglutide is the first long-acting agent used perorally for both diabetes type II20 and obesity." (PMID 37295046, 2023). "DD01, a long-acting dual agonist for GLP-1R/GCGR, is also in a phase 1 clinical trial to investigate the effects on NASH, T2DM, and obesity (A Phase 1 Study of DD01 in Overweight/Obese Subjects with T2DM and NAFLD, NCT04812262, phase 1)." (PMID 37514148, 2023). "Glucagon-like Peptide-1 receptor agonists (GLP-1 RA) and metabolic and bariatric surgery (MBS) both improve cardiovascular outcomes in patients with severe obesity and type-2 diabetes (T2D)." (PMID 36670155, 2023). "Glucagon-like peptide-1 receptor agonists (GLP-1 RAs) are indicated in type 2 diabetes and obesity for their high efficacy in controlling glycaemia and inducing body weight loss, respectively." (PMID 36614945, 2022).
Obesity (continued). "This now constitutes the second GLP1R agonist registered for body weight management, as liraglutide 3 mg was approved by the FDA in 2014 for treatment of adult obesity and in 2020 for obesity in adolescents aged 12–17 years (see Related links)." (PMID 34815532, 2022). "GLP-1 receptor (GLP-1R) signaling is a promising target of obesity and type 2 diabetes treatment, which aims to activate intestinal GLP-1- and GLP-1R-expressing central nervous system circuits resulting from normal eating and GLP-1R agonist drug therapy." (PMID 35208221, 2022). "Based on the first 10 years of GLP-1 therapeutics, the use of GLP-1R agonists for the treatment of T2DM and obesity is growing." (PMID 36077491, 2022). "The development of glucagon-like peptide-1 receptor (GLP-1R) agonists to treat T2DM and obesity/overweight has gained increasing attention." (PMID 36311486, 2022). "In the current study, we showed that the disruption of GLP-1R expressing neurons in the DMH eliminates diurnal feeding pattern, and induces both hyperphagia and severe obesity." (PMID 34098999, 2021). "GLP-1R agonist (GLP-1RA) has been clinically applied in the treatment of type 2 diabetes and obesity." (PMID 34434166, 2021). "This deletion of GLP-1R-positive neurons in the DMH induced hyperphagia, the disruption of diurnal feeding pattern, and obesity." (PMID 34098999, 2021). "In patients with obesity with T2DM, glucagon-like peptide-1 receptor agonists (GLP-1 RA), like semaglutide and dulaglutide, help control hyperglycemia and reduce weight." (PMID 33371340, 2020). "Glucagon-like peptide-1 receptor agonists (GLP-1RAs) are used as anti-diabetic drugs and are approved for obesity treatment." (PMID 32446875, 2020). "First, we confirmed that GLP1R is expressed in VAT from lean and obese patients observing also an increase in its expression levels in both groups of patients with obesity compared to normal-weight volunteers." (PMID 30970605, 2019). "Pharmacological levels of GLP-1 can overcome this resistance and as a result of various GLP-1R agonists have been approved for the treatment of T2DM and obesity." (PMID 31330984, 2019). "The GLP-1R agonist, liraglutide, acts on GLP-1R on ARC POMC neurons to reduce food intake and protect mice from diet-induced obesity." (PMID 31751295, 2019). "Several GLP-1R agonists (e.g., exenatide, liraglutide, and semaglutide) are currently used clinically to treat both T2DM and obesity." (PMID 31330984, 2019). "The MCD model aimed to unravel the effects of the GLP-1R agonist on NASH-like features and restoration of liver mass after PH independently of its effects in reducing obesity." (PMID 30405191, 2018). "In conclusion, our results shed light into the differential effects of a long-acting GLP-1R agonist in improving NAFLD and PLF in the context of obesity and leaness, but decreasing liver mass recovery after PH." (PMID 30405191, 2018). "Dual agonism of GLP-1R/GCGR and very recently triagonism with GLP-1R/GIPR/GCGR have been found to have potent effects to reverse obesity in rodents." (PMID 28223965, 2017). "HRS-7535 is a novel oral GLP-1R agonist evaluated in multiple clinical trials for T2DM and obesity." (PMID 41303737, 2025). "This recent study did not specifically address obesity-related adipose tissue inflammation, and the potential for GLP-1R agonism to directly influence immune cells within adipose tissue and thereby mitigate local inflammation remains an open question." (PMID 40892365, 2025). "Another unimolecular once-weekly dual GLP-1R/GCGR agonist is efinopegdutide (MK-6024), which was able to prove significant reductions in body weight compared to placebo, but no reductions of the HbA1c levels, when investigated in people with obesity and T2DM." (PMID 40004572, 2025). "Preliminary studies suggest that glucagon-like peptide-1 receptor (GLP-1) agonists, used to treat type 2 diabetes and obesity, may decrease alcohol consumption." (PMID 39535805, 2025).
Obesity (continued). "In recent years, glucagon-like peptide-1 receptor agonist (GLP-1RA) and dual glucose-dependent insulinotropic peptide (GIP) and GLP-1 RA have been used as treatments for obesity, but there have been reports raising concerns about muscle weakness due to weight loss." (PMID 40508104, 2025). "In mice with high-fat diet (HFD)-induced obesity, BBR administration increased GLP-1 receptor (GLP-1R) and orexin A expression while decreasing brain neuropeptide Y (NPY) expression, leading to reductions in body weight, plasma lipid levels, and insulin resistance." (PMID 40650060, 2025). "Glucagon-like peptide-1 receptor agonists (GLP-1 RAs) are anti-obesity drugs that were recently shown to be effective in reducing body weight and ameliorating cardiovascular outcomes in patients with overweight or obesity." (PMID 40299361, 2025). "Although our transcriptomic search did not retrieve studies focusing on these pathways, many anti-obesity drugs target GPCRs and peptide hormones (e.g., GLP-1R/GIPR dual agonists)." (PMID 41303351, 2025). "Preclinical studies also demonstrate anticancer effects of contemporary GLP-1R–targeted drugs even in the absence of obesity." (PMID 41178720, 2025). "Effective management necessitates the use of anti-diabetic and anti-obesity therapies that do not compromise leukemia control; glucagon-like peptide-1 receptor agonists (GLP-1 RAs) have shown promise in achieving weight loss while improving glycemic control." (PMID 40292250, 2025). "Glucagon-like peptide-1 receptor agonists (also known as GLP-1 receptor agonists, GLP-1 analogs, GLP1As, and incretin mimetics) are a popular group of medications used in the treatment of type 2 diabetes (T2DM) and obesity." (PMID 40142784, 2025). "Despite the clinical benefits of treating obesity and related complications, glucagon-like peptide-1 receptor agonists (GLP-1RAs) are not yet covered by Medicare Part D, partly due to high drug costs." (PMID 40279111, 2025). "GLP-1R neurons in the PVH receive projections from the NTS, activation of glucagon (Gcg) neurons in the NTS inhibits feeding behaviors, while deletion of PVHGLP-1R neurons increases food intake and decreases locomotor activities, leading to obesity." (PMID 39974186, 2025). "GLP1R agonists, such as liraglutide and semaglutide, originally developed for the treatment of T2DM, have demonstrated significant effectiveness in managing obesity based on their incretin effects and have been approved by FDA for the treatment of obesity." (PMID 39700016, 2024). "Emerging data indicate that glucagon-like peptide-1 receptor agonists could alleviate liver steatosis and DNL in patients with obesity." (PMID 39458565, 2024). "GLP-1R agonists have exhibited potent therapeutic effects on IR, providing benefits for the treatment of polycystic ovary syndrome, neurological dysfunctions, NAFLD, and obesity." (PMID 39456499, 2024). "While data from these trials demonstrate improved efficacy in obesity and T2D through the addition of GCGR agonism to GLP-1R/GIPR agonism, whether these synergistic improvements are evident in kidney-related outcomes remains to be determined." (PMID 38477666, 2024). "Collectively, our findings from islets subjected to acute (Tm) and chronic (obesity) ER stress suggest that chemical chaperones facilitate β-cell response to GLP-1R agonists by enhancing GLP-1R’s utilization of Gq rather than Gs." (PMID 38376482, 2024). "GDF15 level remained unchanged following treatment with liraglutide or lorcaserin in obesity patients, indicating that it does not directly participate in the metabolic feedback pathways activated by GLP1R agonists." (PMID 39700016, 2024). "In the context of appetite regulation, acylation clearly enhances the therapeutic benefits of GLP-1R agonism, suggesting that the ability to cross the BBB is not critical for GLP-1R agonists to access functionally relevant sites for their anti-obesity action." (PMID 38381398, 2024).